MYLK (myosin light chain kinase)
Diseases named in the same sentence as MYLK in open-access papers (continued):
Sharing a sentence is not in itself a finding about the gene and the disease.
tumor (continued). "The results showed that the genes (RAMP1, MYLK and MYH11) of cluster 6 end‐stage were enriched with tumour activation pathways such as cell proliferation and angiogenesis." (PMID 39294858, 2024). "We highlight a small population of cells, a subcluster located in between tumor and myoepithelial populations which coexpress tumor (ERBB2, ABCC11) and myoepithelial markers (MYLK, DST) (a′)." (PMID 38114474, 2023). "RNA transcriptomic analysis showed a gene significantly associated with the low cytoplasmic S100A2 group (AKT3, TAGLN, MYLK, FGD6 and ETFDH), which correlated with tumour development and progression." (PMID 37476187, 2023). "Here we identified high molecular weight myosin light chain kinase, MLCK210, as a key regulator of integrin activation during tumor inflammation and progression." (PMID 35365657, 2022). "The results of the analysis showed that there was a significant decrease in the levels of MYLK‐pS343 and MYL2‐pS19 in tumour lysates from OVCAR8‐shSIK2 cells compared to OVCAR8‐shNC cells, suggesting that SIK2 regulates MYLK/MYL2 phosphorylation." (PMID 35278271, 2022). "A recent study demonstrated that PI3KCG stimulates MLCK210, a high molecular weight type of myosin light chain kinase, which activates Rap1 GTP loading and modifies the conformation of integrin α4β1, which promotes tumor inflammation and progression." (PMID 36468006, 2022). "Here we show that PI3Kγ activates a high molecular weight form of myosin light chain kinase, MLCK210, leading to myosin-dependent activation of Rap1 GTP loading and integrin α4β1 conformational changes that promote tumor inflammation and progression." (PMID 35365657, 2022). "Next, the expression levels of SIK2, MYLK, MYLK‐pS343, MYL2 and MYL2‐pS19 in tumour lysates were assessed by western blot and immunohistochemistry." (PMID 35278271, 2022). "The angiogenesis cluster—besides containing some of the same previous ECM proteins—comprised the angiopoietin ANGPTL4 and other genes that are known to act in tumour-induced angiogenesis (AQP1, RAMP1, HSPB1, MYLK), for a total of 21 entries." (PMID 34439343, 2021). "Of the 16 kinases originally identified in the tumour dataset, 6 were also found to be differentially expressed in the cell line panel: AKT3, MYLK, PRKD1, AXL, NUAK1 and DCLK1." (PMID 33673003, 2021). "In their study, tumor myofibroblasts were identified based on the expression of α-SMA, melanoma cell adhesion molecule (MCAM), myosin light chain kinase (MYLK), and myosin light chain 9 (MYL9)." (PMID 31106200, 2019). "Myoepithelial cells surround the ductal epithelium for structural support, and our results also showed that myoepithelial cell markers, including ACTA2, MYLK, and KRT14, were enriched in the perispatial domain of the tumor, suggesting high-quality detection of tumor contours using our algorithm." (PMID 39965034, 2025). "In fact, the activation of endothelial protein kinases such as myosin light chain kinase (MLCK), which controls myosin light chain (MLC) phosphorylation, prompting stress fibre formation and cytoskeleton contractility, is thought to play a key role in tumour cell migration." (PMID 34209088, 2021). "Identification of seven genes (MYLK, KLK2, KLK3, HAN11, LTF, CSRP1, TGM4) which have their connectivity altered between normal/tumoral conditions may provide novel insights into specific targets against tumor progression." (PMID 19055846, 2008). "Except for MYL9 and MYLK that were oppositely regulated in PHKs versus immortalized keratinocytes and HPV+ tumor cells, none of these genes was DE in normal keratinocytes after CDV exposure." (PMID 23702334, 2013). "In addition, we have not elucidated the precise pathway of tumor-derived MAMDC2 entry into CAFs, the molecular mechanism by which MAMDC2 regulates MYLK expression in CAFs, or its biological effects on CAFs—key questions that require further investigation." (PMID 40427044, 2025).
infection (6 papers, 2012 to 2024). The state of being infected such as from the introduction of a foreign agent such as serum, vaccine, antigenic substance or organism. "Moreover, numerous Ser/Thr kinases (STKs) were either increased (e.g., GRK2, ROCK2, ROCK1, PAK1) or decreased (e.g., BMP2K, TNIK, MYLK, and NRBP1) in expression in the patient samples, suggesting a widespread change in the kinome caused by pathogen infection." (PMID 38389037, 2024). "Additionally, PAstV–4 infection triggered the activation of the extracellular regulated protein kinases/ myosin light-chain kinase (ERK/MLCK) pathway, followed by the down-regulation of tight–junction proteins (occludin and ZO–1) as well as MUC–2 expression." (PMID 38891045, 2024). "VSMCs were infected with adenovirus particles at various multiplicity of infection (MOI), and MYLK mRNA and protein levels were assessed." (PMID 39013850, 2024). "Nystatin/progesteron (cholesterol), blebbistatin (myosin II), and ML-7 (myosin light chain kinase) did not affect HPV-16 internalization or infection, as expected." (PMID 22536154, 2012). "Upon infection of human brain microvascular endothelial cells (HBMEC), cells that form the blood-brain barrier, E. coli K1 induces a reduction in PAK1 activity, resulting in upregulation of myosin light chain kinase (MLCK) activity and increased light chain of myosin II (MLC) phosphorylation." (PMID 28430160, 2017). "Also, actomyosin contractility was not required for entry, as inhibitors of myosin II and myosin light chain kinase only mildly reduced infection consistent with their role in transport of HPV-16 along filopodia by actin retrograde flow." (PMID 22536154, 2012).
cardiovascular diseases (2 papers, 2021 to 2024). "Although this SNP was not replicated, the Human MYLK gene is an attractive candidate for cardiovascular diseases." (PMID 33531528, 2021).
inflammation (2 papers, 2014 to 2022). Aberrant reaction of the microcirculation characterized by movement of fluid and leukocytes from the blood into extravascular tissues. "The genes BMP6, CFB and MYLK have previously been associated with airway inflammation and hyperresponsiveness." (PMID 24475887, 2014). "The intravenous injection of MYLK peptide inhibitor reduced lipopolysaccharide-induced lung inflammation in mice." (PMID 36387401, 2022).
bacterial infections (1 paper, 2024). "The potential applicability of ML-7, an inhibitor of myosin light chain kinase (MLCK), in bacterial infections has not been reported to date, and studies on ML-7 are still in the in vitro phase, but its potential as a novel tigecycline adjuvant to reverse drug resistance should not be overlooked." (PMID 38399231, 2024).
connective tissue disorder (1 paper, 2023). A disease involving the connective tissue. "Our patient had no dysmorphic signs or features to suggest inherited connective tissue disorders but had a MYLK VUS." (PMID 36834577, 2023).
prostate (1 paper, 2025). "Interestingly, MYLK, MYH11, and FLNC were identified as pivotal genes in studies of the immune microenvironment, and MYLK and FLNC were found to be associated with prostate pathogenesis and prognosis." (PMID 39762799, 2025).
respiratory diseases (1 paper, 2024). "Animal models have reported that ML-7, a potent myosin light-chain kinase (MLCK) inhibitor, impedes neutrophilic inflammation caused by LPS in various respiratory diseases." (PMID 38526572, 2024).
MYLK also shares sentences with these, for which no sentence is quoted: injury (3 papers); Loeys-Dietz syndrome (3); atrial fibrillation (2); cardiomyopathy (2); dementia (2); endothelial dysfunction (2); kidney cancer (2); megacystis-microcolon-intestinal hypoperistalsis syndrome (2); Thoracic Aortic aneurysm and dissection (2); advanced heart failure (1); airway hyperresponsiveness (1); allergic rhinitis (1); Amoebiasis (1); and glucocorticoid deficiency (1); aortic insufficiency (1); Arrhythmia (1); Arterial stenosis (1); bowel obstruction (1); brain edema (1); carcinoma in situ (1); centronuclear myopathy (1); cervical adenocarcinoma (1); co-infection (1); colonic disease (1); digestive system tumors (1); Duodenal stenosis (1); E. coli infection (1); Ehlers-Danlos syndrome (1); epilepsy (1); essential hypertension (1).
A further 53 diseases each share a sentence with MYLK in 1 paper.